ATF3 (activating transcription factor 3)
Diseases named in the same sentence as ATF3 in open-access papers (continued):
Sharing a sentence is not in itself a finding about the gene and the disease.
tumor (continued). "This process was achieved by restoring the ATF3 tumor suppressor and restraining the AKT signaling pathway." (PMID 37433803, 2023). "Flow cytometry analysis revealed an elevation of the anti-inflammatory M2 cardiac macrophages using the F4/80 + CD206+ markers in tumor-bearing mice compared to tumor-free ATF3 tg mice." (PMID 37759510, 2023). "It is expected that combining conventional drugs targeting PCC with options reducing ATF3 expression is expected to be effective in eradicating tumor cells and warrants further study." (PMID 37833290, 2023). "Collectively, these data show a potential role of cardiac M2 macrophages in mediating the beneficial effect in tumor-bearing ATF3 transgenic mice." (PMID 37759510, 2023). "ATF3 and JDP2 deficiency in cancer-related fibroblasts enhances tumor growth via SDF-1 transcription." (PMID 36741260, 2023). "Here we demonstrate that expression of ATF3 in DCs has an important function in stimulating tumor growth." (PMID 36333297, 2022). "For instance, CDCA8 knockdown inhibits HCC development and stemness by restoring the ATF3 tumor suppressor and inactivating AKT/β-catenin signaling." (PMID 36302799, 2022). "In conclusion, the oncogenic role of miR-760 and tumor suppressor role of ATF3 help to explain the potential regulatory mechanism of METTL1 in BCa." (PMID 36396627, 2022). "Sodium selenite treatment upregulated pro-apoptotic, apoptotic, and tumor suppressor genes such as ATF3, FOSB, GADD45B, DUSP8 and ACHE, and downregulated tumor cell survival genes such as SCD, LRP1, RAB31, SRPX2, PDK1 and CSGALNACT1." (PMID 36059619, 2022). "Taken together, ATF3 down-regulates the activity of NF-κB and, as a result, suppresses the tumor in HPV16-infected cells." (PMID 36522783, 2022). "Compared to normal tissues (n = 19), ATF3 at a higher expression level in primary tumor tissues (n = 408) was along with a higher disease-free survival rate in the TCGA database." (PMID 36396627, 2022). "And in this study, we confirmed the tumor-suppressive role of ATF3 in BCa, showing that overexpression of ATF3 repressed the proliferation and migration of BCa cells." (PMID 36396627, 2022). "TG sections from tumor-bearing male mice had more DiI-positive ATF3-IR neurons compared to tissue from male PID14 sham (p = 0.001) as well as compared to tissue from MOC2 tumor-bearing female mice (p = 0.032)." (PMID 36172037, 2022). "We did not observe any significant changes in lumbar DRG CD68 density or ATF-3 expression in samples from tumor-bearing vs control mice (n = 7–12/group from ≥ 3 biological replicates)." (PMID 35962398, 2022). "There was a 4- and 2.5-fold increase in Atf3 expression in tumor-bearing male (p < 0.0001) and female (p = 0.002) mice, respectively, compared to sex-matched PID14 sham mice." (PMID 36172037, 2022). "This difference was not seen in DCs isolated from either lymph nodes or spleens indicating that factors present in the tumor microenvironment induce ATF3 in DCs." (PMID 36333297, 2022). "ATF3 is known to exhibit dichotomous functions both as an oncogene and tumor suppressor, depending upon cancer subtype or context of its upregulation." (PMID 36131935, 2022). "The differential expression of ATF3 was further confirmed in Linc01612 overexpressed cells and in subcutaneous tumor tissues." (PMID 35541917, 2022). "In the present study, our data demonstrate that ATF3-induced miR-21–3 p upregulation contributed to the efficacy of anti-PD-1 immunotherapy by facilitating tumor cell ferroptosis via the suppression of the novel target TXNRD1 and lipid peroxidation." (PMID 35738798, 2022). "EGR1 encodes early growth response, critically participating in neovascularization, tumor angiogenesis, and growth, together with ATF3, which can influence the limbal epithelial cell proliferation." (PMID 36187094, 2022).
tumor (continued). "Activating transcription factor 3 (Atf3) is a direct transcriptional target of Sd, which is significantly upregulated in Ras driven tumor formation." (PMID 35883668, 2022). "Here we report that this suppression is induced by tumor microenvironment-derived factors, which activate the activating transcription factor-3 (ATF3) transcription factor and downregulate cholesterol 25-hydroxylase (CH25H)." (PMID 36333297, 2022). "In this work, we show that factors present in the tumor microenvironment induce ATF3 and decrease the levels of CH25H in the intratumoral DCs." (PMID 36333297, 2022). "As a novel tumor suppressor mediator, activating transcription factor 3 (ATF3) has recently aroused an interest in its possible therapeutic applications in various cancers." (PMID 36522783, 2022). "When ATF3 activity was inhibited by small interfering ribonucleic acid (siRNA) activity, gamma‐tocotrienol was able to restore ATF3‐induced apoptotic effects which in turn downregulated tumor proliferation." (PMID 35719120, 2022). "Previously, we identified a number of Wnt/β-catenin signaling pathway genes and their targets in this BK5.ATF3 tumor model that are differentially expressed." (PMID 33652981, 2021). "Compared with normal samples, except for the down-regulation of ATF3, other genes were up-regulated in tumor tissues." (PMID 34790227, 2021). "We found that low levels of ATF3 were associated with lower OS and DFS in patients with HCC, suggesting that the gene acts as a tumor suppressor." (PMID 33407456, 2021). "In summary, we analyzed DEGs in anisomycin treated DLD-1 cells for the first time and found that several tumor-suppressor genes, including ATF3, were transiently induced at 3 h after treatment." (PMID 34151031, 2021). "In many cancers, ATF3 expression is enhanced by anti-tumor agents and has positive effects on apoptosis." (PMID 33921748, 2021). "Taken together, these results suggest that ATF3 negatively modulates TSCC tumor growth and differentiation in vivo through the expression level of IFI6 or IFI27." (PMID 33539340, 2021). "To confirm the RNA sequencing or normalized probe results obtained from the database, we examined 46 paired GC and normal tissue samples by RT-qPCR analysis, and ATF3 mRNA was conspicuously lower in the tumor tissues (71.7%, 33 of 46 pairs, p = 0.0003)." (PMID 34728784, 2021). "ATF3 expression was significantly related to gender, age, tumor size, Fuhrman grade, tumor stage, and metastasis in patients with ccRCC." (PMID 33816467, 2021). "Taken together, these results suggest that ATF3 negatively regulates tumor progression probably through specific downstream targets." (PMID 33539340, 2021). "The antiproliferative effects were driven by the upregulation of tumor suppressive ATF3 and GADD34, whereas p-Akt and β-catenin, key regulators of stemness, were repressed." (PMID 33801424, 2021). "Our findings suggest that tumor suppressive genes, such as ATF3, were activated early in the sequence of events leading to the inhibitory effect of anisomycin on cell proliferation." (PMID 34151031, 2021). "TRPV1 stimulation also triggers tumor cell death via the activating transcription factor-3 (ATF3)-controlled branch of the endoplasmic reticulum stress pathway." (PMID 34458247, 2021). "The results demonstrate that ATF3 plays a tumor suppressing function in TSCCs through the negative regulation of its novel targets IFI6 and IFI27." (PMID 33539340, 2021). "ATF3 expression was correlated with tumor size (p = 0.006), serosal invasion (p = 0.014), peritoneal dissemination (p = 0.049) and tumor invasion depth (p = 0.038)." (PMID 34728784, 2021). "Taken together, our results clearly reveal that ATF3 plays a role in inhibiting tumor growth in patients with HCC." (PMID 33407456, 2021).
tumor (continued). "Using qPCR, the expression of ATF3 was detected in 93 patients with ccRCC, including 24 paired normal and tumor tissues, which were used to further compare ATF3 expression through western blotting and immunohistochemistry." (PMID 33816467, 2021). "Tumor weights of mice bearing miR-222 inhibitor + si-ATF3 were much heavier after 4 weeks than controls with poor expression of miR-222 alone." (PMID 33794833, 2021). "Ki-67 staining showed that there were many more Ki-67 positive cells (red arrows) in tumor tissues with the deletion of ATF3 (SG1 or SG2)." (PMID 33539340, 2021). "We analyzed the ATF3 mRNA levels in tumor and corresponding normal tissues of different tumors types using ONCOMINE and TIMER." (PMID 33407456, 2021). "The same condition increased the protein levels of tumor-suppressive ATF3 and GADD34 and inactivated AKT/β–catenin signaling, which plays an important role in cell growth and stemness, reflecting a reduction in sphere-forming capacity." (PMID 33801424, 2021). "In this study, by comparing data from public databases, we found that ATF3 expression was significantly decreased in ccRCC tumor tissues." (PMID 33816467, 2021). "Genes regulated by EHF_extended, BATF_extended, and CD59_extended were highly upregulated in advanced tumor cells, while genes regulated by ATF3, JUNB_extended, and FOSB_extended were upregulated in early tumor cells." (PMID 33783985, 2021). "The results observed in these studies were controversial, suggesting that the role of Wnt/β-catenin signaling in the transcriptional regulation of ATF3 in tumor cells is quite complex." (PMID 34728784, 2021). "In our analysis, EIF4EBP1, IMP3, ATF3, SEC11A and SHC1 also exhibited different expression between BC and non-tumour samples, and were significantly associated with the tumour type, invasive progression, or tumour grade (SupplementaryFigure S2)." (PMID 34187252, 2021). "More remarkably, analysis of cell apoptosis and tumorigenesis in mice revealed that ATF3 has proapoptotic effect on cancer cells and has limited effect on tumor growth." (PMID 35052581, 2021). "In this study, our clinical pathological and TCGA data analysis of ccRCC demonstrated that ATF3 was significantly downregulated in tumors compared to in adjacent non-tumor tissues." (PMID 33816467, 2021). "Most studies focus on the role of ATF3 in cancers and validate its critical effects on cell growth, apoptosis, cell cycle arrest, metastasis, and acquired drug resistance in a variety of tumor cells." (PMID 33315500, 2021). "Tumor peritoneal metastasis models were established and revealed that the number of peritoneal nodules in the ATF3-knockdown AGS group was significantly greater than that in the control group (-iii)." (PMID 34728784, 2021). "Abundant data are available regarding the dual roles of ATF3 in the protection of both normal and cancer cells from further transformation and in the promotion of tumor progression." (PMID 33407456, 2021). "Consistent with our study, the tumor suppressing function of ATF3 has been reported in multiple studies with different types of tumors." (PMID 33539340, 2021). "We observe an enrichment for Fra1, Fra2, JunB, Atf3 and AP-1 in tumours with Gleason pattern 3 whereas tumours with Gleason pattern 4 show an enrichment for FOXA1, HOXB13 and CDX2." (PMID 34911933, 2021). "Results from GO analysis further revealed that among these ASC-J9® elevated genes, only 11 genes, including ATF3, are responsible for the tumor suppression." (PMID 33390173, 2021). "Additional rescue experiments in our study indicated that AKT1 knockdown reversed the supporting role of si-ATF3 in tumor growth and immune escape in CRC." (PMID 33794833, 2021).
tumor (continued). "It has been extensively studied in tumor cells, and the role of ATF3 in tumor cells has been shown to be cell type-specific." (PMID 32373541, 2020). "A significant correlation between ATF3 expression level and tumor-node-metastasis stage/lymph node metastasis/invasion/number of metastatic lymph nodes was also noted." (PMID 32922364, 2020). "To test that possibility, we screened several compounds that were previously reported to induce ATF3 expression and to play anti-tumor roles, including cyclosporine A (CsA), cisplatin, metformin/phenformin, and sulfuretin." (PMID 32373541, 2020). "Our findings further support that ATF3 in stromal fibroblasts plays a tumor suppressing function in the skin." (PMID 32373541, 2020). "It is therefore established that ATF3 can rewire the mammary gland processes by affecting several downstream pathways involved in tumor initiation and progression." (PMID 33050633, 2020). "It has been shown that ATF3 can be either an oncogene or a tumor suppressor gene depending on the type of tumor." (PMID 32373541, 2020). "The integrated stress response mediators ATF4 and ATF3 have been known to impact tumor cell survival in part through regulation of the Bcl-2 family members of proteins." (PMID 32664214, 2020). "Further immunohistochemical analysis of patient tumor samples showed that ATF3 expression in stromal mononuclear cells is correlated with poor clinical outcomes." (PMID 32922364, 2020). "ATF3 is one of the crucial stress-responsive factors and acts as either a tumor suppressor or oncoprotein in cancer-type dependent manner." (PMID 32398095, 2020). "It thus seems that the role of ATF3 in cancer progression is highly context dependent and tumor-type specific." (PMID 33050633, 2020). "In the presence of E2, all mice in the three groups had to be sacrificed due to tumor progression, with the two ATF3 knockouts reaching the humane endpoints slower than the WT." (PMID 33050633, 2020). "RT-qPCR was used to detect the expression of LINC01600, JUND, ZFP36, and ATF3 in tumor tissues of 40 PCa patients collected in our hospital." (PMID 32318351, 2020). "While tumor size in ATF3-KO mice was similar to WT mice, the tumors developed in JDP2-KO mice were significantly larger, consistent with previous publications." (PMID 30670778, 2019). "To investigate the impact of host JDP2 and ATF3 expression on tumor growth and proliferation, we generated mice with double deficiency of these proteins by consecutive crossing of JDP2−/− and ATF3−/− strains." (PMID 30670778, 2019). "While the tumor compromises both cancer cells and stroma, here we studied the role of ATF3 and JDP2 in the stroma." (PMID 30670778, 2019). "As ATF3 and JDP2 compensate each other’s function, we studied the double deficiency of ATF3 and JDP2 in the stromal tumor microenvironment." (PMID 30670778, 2019). "We identified that the deficiency of ATF3 and JDP2 elevates stromal cell-derived factor 1 (SDF-1) secretion by CAFs found in the tumor stroma, ultimately increasing tumor growth." (PMID 30670778, 2019). "Collectively, these results indicate that the double deficiency in ATF3 and JDP2 specifically affects fibroblasts in the tumor environment and the function of tumor vasculature, possibly leading to changes in tumor development and size." (PMID 30670778, 2019).
tumor (continued). "The results indicated that the average weights of livers with tumor xenografts were significantly higher in mice injected with ATF3-silenced cells." (PMID 30376856, 2018). "When the stroma starts to express Atf3, it reflects a reactive tumor microenvironment and dysregulated immune function." (PMID 30373101, 2018). "Re‐analysis of these key molecules in tumour tissues indicated that phosphor‐eIF2α, ATF3 and ATF4 were remarkably induced in TSA‐treated mice, in agreement with the results observed in cultured cells." (PMID 29327812, 2018). "In this study, we identified ATF3 as a tumor suppressor for inhibiting cell proliferation and metastasis in HCC." (PMID 30376856, 2018). "Our findings indicate that ATF3 functions as a tumor suppressor in HCC through targeting and regulating CYR61." (PMID 30376856, 2018). "ATF3 has been ascribed roles as diverse as tumor suppression, development, and cell survival, however, little is known regarding its role specifically in SLE." (PMID 29593737, 2018). "Presumably, Atf3, as a hub in the adaptive-response network, will be a linchpin for seemingly different stressors, such as tumor signals, chemotherapy, and traumatic injury, to enhance cancer progression and metastasis." (PMID 30373101, 2018). "Reactivation of ATF3 by pracinostat is a determining factor in the tumor response to the HDACi therapy and ATF3 was a biomarker of tumor response." (PMID 30376856, 2018). "The results indicated that the average weights of livers with tumor xenografts were significantly lower in mice injected with cells overexpressing ATF3." (PMID 30376856, 2018). "The controversial roles of ATF3 were demonstrated to occur in both oncogenesis and tumor suppression." (PMID 28402947, 2017). "Our RKO and HCT116 results were consistent with the other two independent studies, where ATF3 appeared to promote tumor growth and migration in HT29 cell line by either ATF3 antisense oligonucleotide or adenovirus-mediated overexpression of ATF3." (PMID 28402947, 2017). "It is also clear that a number of the candidate drivers including MXI1, SIN3A, THAP1 and ATF3 are down-regulated in PRAD tumours." (PMID 28592290, 2017). "Remarkably, Dkk-3 is able to up-regulate ATF3 and enhance Smad3 phosphorylation in tumor cell lines." (PMID 28352232, 2017). "In normal tissues, ATF3 promotes both apoptosis and cell proliferation, while in neoplasms it has been identified as either an oncogene or a tumor suppressor, depending on the context of tumors." (PMID 28402947, 2017). "Target genes of ATF3 regulation which have an important impact on tumor phenotype and prognosis were validated by colorectal cell line experiments." (PMID 28402947, 2017). "Here we focused on ATF3 protein expression in tumor cells, The TCGA mRNA expression came from mixed cell populations, which contributed to the ambiguity of expression due to subtype composition, especially for lower transcription factor expression." (PMID 28402947, 2017). "In CRC models, ATF3 is a tumor suppressor through up-regulated heat-shock protein 90 (Hsp90) inhibition tumor growth." (PMID 28402947, 2017). "In gene expression arrays, the overexpression of TLR4 in tumor cells correlated with gene expression of ATF-3, IL-6, CDH13, CXCL-1 and TFPI." (PMID 28982115, 2017). "Because ATF3 functions in regulation of cancer cell survival and apoptosis depending on tumor types, its function in HCC was still unclear." (PMID 26917416, 2016).